ORAI2 (ORAI calcium release-activated calcium modulator 2)
Description:
Pore-forming subunit of inward rectifying Ca(2+) release-activated Ca(2+) (CRAC) channels. Assembles with ORAI1 and ORAI3 to form hexameric CRAC channels that mediate Ca(2+) influx upon depletion of endoplasmic reticulum Ca(2+) store and channel activation by Ca(2+) sensor STIM1, a process known as store-operated Ca(2+) entry (SOCE). Various pore subunit combinations may account for distinct CRAC channel spatiotemporal and cell-type specific dynamics. ORAI1 mainly contributes to the generation of Ca(2+) plateaus involved in sustained Ca(2+) entry and is dispensable for cytosolic Ca(2+) oscillations, whereas ORAI2 and ORAI3 generate oscillatory patterns. CRAC channels assemble in Ca(2+) signaling microdomains where Ca(2+) influx is coupled to calmodulin and calcineurin signaling and activation of NFAT transcription factors recruited to ORAI1 via AKAP5. CRAC channels are the main pathway for Ca(2+) influx in T cells and promote the immune response to pathogens by activating NFAT-dependent cytokine and chemokine transcription.
Synonyms: C7orf19; CBCIP2; TMEM142B; FLJ12474; FLJ14733; H_NH0514P08.8; MEM142B
Tractability: Antibody: UniProt places it where antibodies can reach, with high confidence; its Gene Ontology location is reachable by antibodies, with high confidence; UniProt predicts a signal peptide or a membrane-spanning region. PROTAC: ubiquitination databases record sites on it; a small molecule that binds it is known.
Gene: Protein-coding gene on chromosome 7 (102,433,106 to 102,456,825, forward strand). Ensembl gene ENSG00000160991.
Subcellular location: Cell membrane
Subcellular location (Human Protein Atlas): Mitochondria; Nucleoplasm; Cytosol
Pathways (Reactome):
Hemostasis: Elevation of cytosolic Ca2+ levels
Immune System: Antigen activates B Cell Receptor (BCR) leading to generation of second messengers
Muscle contraction: Ion homeostasis
Gene Ontology:
Molecular function: protein binding; store-operated calcium channel activity
Biological process: store-operated calcium entry; calcium ion transmembrane transport
Cellular component: cytosol; mitochondrion; nucleoplasm; plasma membrane; membrane
Genetic constraint (gnomAD): Loss-of-function variants: 10 observed, 16.5 expected, observed/expected ratio (o/e) 0.61, 90% interval 0.37 to 1.03. The upper end of that interval is the gene's LOEUF score, 1.03, which puts it in group 4 of 6, group 1 being the genes least tolerant of losing a copy. Missense variants: 238 observed, 361.61 expected, observed/expected ratio (o/e) 0.66, 90% interval 0.59 to 0.73. Synonymous variants: 150 observed, 162.1 expected, observed/expected ratio (o/e) 0.93, 90% interval 0.81 to 1.06.
Homologues: Orthologues: chimpanzee ORAI2 (100% identical), macaque ORAI2 (99% identical), dog ORAI2 (98% identical), pig ORAI2 (97% identical), rabbit ORAI2 (96% identical), mouse Orai2 (95% identical), rat Orai2 (95% identical), guinea pig ORAI2 (94% identical), zebrafish orai2 (84% identical), tropical clawed frog orai1 (82% identical), Drosophila melanogaster Orai (50% identical), Caenorhabditis elegans orai-1 (37% identical). Paralogues in human: ORAI1 (63% identical), ORAI3 (61% identical).
Diseases named in the same sentence as ORAI2 in open-access papers:
ORAI2 is named in the same sentence as 47 diseases in open-access papers, as found by Europe PMC text mining. Sharing a sentence is not in itself a finding about the gene and the disease. The quoted sentences say what the papers report.
breast carcinoma (10 papers, 2018 to 2026). "Finally, Orai2 plays an important role in cell cycle progression, which might underlie chemoresistance in breast cancer cells." (PMID 35008277, 2021). "We have found that the breast cancer stem cells (BCSC) derived from MCF7, SKBR3 and MDA-MB-231 breast cancer cell lines overexpressed Orai1 and Orai2 as compared to breast stem cells (BSC) derived from the non-tumoral cell line MCF10A (p < 0.001; n=6)." (PMID 37945647, 2023). "The group indicated that based on their findings, Orai2 plays a crucial role in the pathophysiology of breast cancer subtypes with an elevated Orai2 expression profile." (PMID 37259313, 2023). "Nevertheless, the role of the Orai2 channel in cancer is still less studied, though it has been shown as an actor of cell cycle progression in breast cancer and promoter of metastases in gastric cancer." (PMID 37576552, 2023). "Here we provide evidence of the heterogeneous expression of Orai1 and Orai2 between different breast cancer cell lines which leads to the identification of breast cancer cells with high and low Orai1:Orai2 expression ratios." (PMID 35008277, 2021). "In Summary, our results reveal the great heterogeneity in Orai1 and Orai2 channel expression between different breast cancer cell lines." (PMID 35008277, 2021). "Here we provide evidence for a heterogeneous expression of Orai2 among different breast cancer cell lines." (PMID 35008277, 2021). "Here, we provide evidence for a different expression of Orai2 and a different relative Orai1:Orai2 expression profile in different breast cancer cell lines." (PMID 35008277, 2021). "We have further analyzed the role of Orai2 on carbachol (CCh)-induced Ca2+ oscillations in SKBR3, BT20 and T47D cells, as representative of breast cancer cells with low and high Orai1:Orai2 expression ratios." (PMID 35008277, 2021). "Altogether, these findings indicate that, in breast cancer cells with a high Orai2 expression, Orai2 plays a relevant functional role in agonist-evoked Ca2+ signals, cell proliferation and apoptosis resistance." (PMID 35008277, 2021). "Moreover, STIM2 and Orai2/3 are relevant to cancerous processes, whereby Orai2 was, for instance, reported to promote migration and metastasis in gastric cancer and is important for cell cycle progression of breast cancer cells." (PMID 35681544, 2022). "However, the expression profile and functional role of Orai2 in breast cancer cells remains unclear." (PMID 35008277, 2021). "Next, we investigated whether Orai2 plays a relevant role in cell cycle progression and apoptosis resistance in BT20 and SKBR3 cells, which exhibit the greater Orai2 expression among the breast cancer cell lines investigated, and also in T47D, which shows a low Orai2 expression." (PMID 35008277, 2021). "Among the exceptions are ER+ breast cancer cells and NSCLC cells, where SOCE is strongly dependent on the Orai3 expression, while knockdown of Orai1 or Orai2 has a minor effect if any, meaning that Orai3 plays a predominant role in SOCE in these cells." (PMID 34768857, 2021). "Next, we explored the role of Orai2 in TG-induced SOCE in the breast cancer cell lines that exhibit low (SKBR3 and BT20) or high (T47D) Orai1:Orai2 expression ratios." (PMID 35008277, 2021). "Analysis of the expression of Orai1 and Orai2 at the transcript level was carried out by qRT-PCR and revealed a greater expression of Orai1 mRNA transcript in all the breast cancer cell lines investigated as compared to non-tumor MCF10A cells (p < 0.01)." (PMID 35008277, 2021). "Interestingly, the mRNA levels of Orai2 and Orai3 were similar in breast cancer-derived cell lines and nonmalignant mammary epithelial cell lines." (PMID 37759164, 2023).
gastric cancer (10 papers, 2021 to 2025). A primary or metastatic malignant neoplasm involving the stomach. "ORAI2 enhances metastasis ability of gastric cancer cells by inducing FAK-mediated MAPK/ERK activation." (PMID 40104507, 2025). "NSUN2 regulates ORAI2 mRNA stability, then promotes ORAI2 expression and further peritoneal metastasis and colonization of gastric cancers." (PMID 38672434, 2024). "It has been reported that ORAI2 promotes the dissociation of FAs at the posterior margin of gastric cancer cells by inducing FAK-mediated MEK/ERK activation and enhancing the metastatic ability of gastric cancer cells." (PMID 37460470, 2023). "NSUN2 activates the ORAI2 expression, promoting gastric cancer metastasis." (PMID 38468490, 2024). "Elevation of Orai2 is positively correlated with lymph node metastasis of gastric cancer (GC)." (PMID 36046433, 2021). "NSUN2 boosts ORAI2 mRNA stability through m5C modification and enhances ORAI2 expression via YBX1 recognition, promoting peritoneal metastasis and the spread of gastric cancer." (PMID 39791162, 2025). "In gastric cancer, YBX1 serves as a 5mC reader and stabilizer of ORAI2 mRNA, resulting in the upregulation of E2F1, promoting peritoneal metastasis and colonization of gastric cancer." (PMID 38255791, 2024). "For example, ORAI2 modulates PI3K/AKT signaling to aggravate tumor growth and metastasis in gastric cancer." (PMID 38955795, 2024).
prostate carcinoma (4 papers, 2013 to 2018). A carcinoma that arises from epithelial cells of the prostate gland. "For Orai1, 5 out of 7 studies reported a slight elevation in ORAI1 gene expression in prostate cancer tissue, only 2 out of 12 studies reported an elevation in ORAI2 gene expression." (PMID 29951353, 2017). "This article summarizes what is known about the dysregulation of the key molecular players involved in SOCE (STIM1, STIM2, Orai1, Orai2, and Orai3) and the negative regulator TRPM4 in prostate cancer." (PMID 29951353, 2017). "We compare expression levels of STIM1, STIM2, Orai1, Orai2 and Orai3 in tumorous and non-tumorous tissue from prostate cancer patients." (PMID 24240085, 2013). "We thus determined relative STIM and Orai expression levels in non-tumorous and tumorous tissue from 13 prostate cancer patients by qRT-PCR, from which 13 expressed detectable levels of STIM1, STIM2 and Orai1 and 11 detectable levels of Orai2 and Orai3." (PMID 24240085, 2013).
oral cancer (3 papers, 2020 to 2025). "The SNV rs112265837 is located in the ORAI2 gene which has been previously associated with calcium channel activity in the plasma membrane and oral cancer cell migration." (PMID 41006734, 2025). "ORAI2 regulates the migration and colonization of oral cancer cells by inhibiting Akt/mTOR/NF-κB signaling pathway." (PMID 33680910, 2020). "Furthermore, previous studies have reported that silencing of Orai1 and Orai2 expression attenuate the Akt/mammalian target of rapamycin/NF-κB pathway in oral cancer cells, further supporting a role for Orai channels in NF-κB activation." (PMID 36623731, 2023).
Alzheimer disease (2 papers, 2022 to 2023). A progressive, neurodegenerative disease characterized by loss of function and death of nerve cells in several areas of the brain leading to loss of cognitive function such as memory and language. "Of note, another study showed, in a cell model of Alzheimer’s disease, that downregulation of Orai2 increases SOCE and decreases amyloid-beta accumulation, which suggests a potential benefit for Orai2 knockdown in Alzheimer’s disease." (PMID 35821821, 2022).
Autoimmunity (2 papers, 2017 to 2021). The occurrence of an immune reaction against the organism's own cells or tissues. "In vivo, Orai1/Orai2 double-deficient mice have impaired T cell-dependent antiviral immune responses, and are protected from T cell-mediated autoimmunity and alloimmunity in models of colitis and graft-versus-host disease." (PMID 28294127, 2017). "To elucidate the role of Orai1 and Orai2 in autoimmunity, we used an adoptive transfer model of IBD that tests the function of ORAI1 and ORAI2 in pathogenic donor T cells." (PMID 28294127, 2017).
dementia (2 papers, 2021 to 2022). Loss of intellectual abilities interfering with an individual's social and occupational functions. "Furthermore, two ADAR3-bound transcripts we identified in this study, ORAI2 and STY11, were recently identified from brain tissue samples as transcripts where the editing level in the 3′ UTR correlated with the degree of dementia in individuals with AD." (PMID 35850307, 2022).
glioblastoma (2 papers, 2019 to 2022). The most malignant astrocytic tumor (WHO grade IV). "One GEO database (GSE23806) was used to analyze the expression of Orai2 in glioblastoma stem-like cell lines, conventional glioma cell lines, neurospheres, and primary tumors (corresponding tumor tissue of glioblastoma patients)." (PMID 31772693, 2019). "We found that Orai2 expression was relatively high in glioblastoma stem-like cell lines and neurospheres compared to conventional glioma cell lines and primary tumors." (PMID 31772693, 2019). "However, to date, there have been few reports on the specific mechanism of action of Orai2 in glioblastoma, so our bioinformatics analysis of Orai2 is very meaningful." (PMID 31772693, 2019). "To explore the role of Orai2 in glioblastoma (GBM), we investigated the key pathways and genes in Orai2-mediated GBM by bioinformatic analyses." (PMID 31772693, 2019). "Unfortunately, we are unable to discern the impact of ADAR3 on editing of these transcripts from our analysis of RNA isolated from U87 glioblastoma cell lines, as little editing of STY11 is observed in these cells and read counts for ORAI2 are very low." (PMID 35850307, 2022).
astrocytomas (1 paper, 2019). "When we classified the data according to glioma tissue type in the French and TCGA datasets, we found that the expression level of Orai2 in GBMs was also higher than that of astrocytomas, oligoastrocytomas, and oligodendrogliomas." (PMID 31772693, 2019).
basophilic leukemia (1 paper, 2021). "In addition, unlike Orai1, majority of the Orai2 is found in intracellular sites in rat basophilic leukemia (RBL-2H3) cells and the possibility that intracellular Orai2 could modulate Ca2+ influx has been suggested but the mechanism is not clear." (PMID 35126366, 2021).
brain infarction (1 paper, 2022). Tissue necrosis in any area of the brain, including the cerebral hemispheres, the cerebellum, and the brain stem. "We have previously shown that Orai2 is crucial for ischemic neuronal cell death and that its absence can substantially delay progressive brain infarction before recanalization." (PMID 36012752, 2022).
Cerebral ischemia (1 paper, 2022). Restriction of arterial blood supply to the brain associated with insufficient oxygenation to support the metabolic requirements of the tissue. "We induced focal cerebral ischemia in Orai2-deficient (Orai2-/-) mice by middle cerebral artery occlusion (MCAO)." (PMID 36012752, 2022).
chronic kidney disease (1 paper, 2022). Impairment of the renal function secondary to chronic kidney damage persisting for three or more months. "Seventeen-nucleotide tRF-3b can regulate Ca2+ ion transport by interacting with mRNA ORAI2 or CACNG proteins and modulating the activity of CYP20A1 and GAS7, proteins associated with kidney diseases, such as kidney nephropathy, proteinuria and chronic kidney disease." (PMID 35409004, 2022).
colitis (1 paper, 2017). Inflammation of the colon. "Abolishing SOCE by combined deletion of Orai1 and Orai2 resulted in severe defects in T cell function in vitro and T cell-mediated immune responses in vivo including antibody production after viral infection, colitis and GvHD." (PMID 28294127, 2017). "Furthermore, Orai1/Orai2-deficient T cells did not cause immunopathology in adoptive transfer models of colitis and GvHD." (PMID 28294127, 2017).
colon cancer (1 paper, 2016). "Recently, human colon cancer cells have been shown to present an increase of SOCE, related to an increase in TRPC1, Orai1, Orai2, Orai3 and STIM1 expressions." (PMID 27102434, 2016).
glioma (1 paper, 2019). A benign or malignant brain and spinal cord tumor that arises from glial cells (astrocytes, oligodendrocytes, ependymal cells). "We revealed that Orai2 expression was significantly higher in GBM (WHO IV) than lower-grade glioma (WHO II and WHO III)." (PMID 31772693, 2019). "As a prognostic factor, Orai2 is obviously activated in the classical and mesenchymal subtypes of GBM and promotes glioma cell self-renewal, apoptosis, and EMT-like by the JNK pathway." (PMID 31772693, 2019). "We discovered that Orai2 was markedly upregulated in GBM compared to normal brain samples and lower-grade gliomas (LGG)." (PMID 31772693, 2019). "Compared with lower-grade glioma (WHO II and WHO III), Orai2 expression was significantly increased in GBM from the TCGA dataset (Student's t-test, P < 0.001)." (PMID 31772693, 2019). "However, as a homolog of Orai1, the role of Orai2 in gliomas has not yet been elucidated." (PMID 31772693, 2019).
hyperreactivity (1 paper, 2023). "Together, our data suggest that Orai1 and Orai2 support pathogenic ILC2 effector function in vivo, driving the development of ILC2-dependent airway hyperreactivity." (PMID 37752127, 2023). "The results indicated that Orai1 and Orai2 are expressed on activated pulmonary ILC2s and may play a role in the development of airway hyperreactivity." (PMID 37752127, 2023).
idiopathic pulmonary arterial hypertension (1 paper, 2021). A sporadic form of pulmonary arterial hypertension (PAH) characterized by elevated pulmonary arterial resistance leading to right heart failure. "It has been reported that the expression level of Orai2 is significantly increased in pulmonary arterial smooth muscle cells from patients with idiopathic pulmonary arterial hypertension." (PMID 34595206, 2021). "Enhanced expression of the Orai2 transcript has also been found in endothelial cells of lung explants obtained from patients with idiopathic pulmonary arterial hypertension." (PMID 34595206, 2021).
Immunodeficiency (1 paper, 2017). Failure of the immune system to protect the body adequately from infection, due to the absence or insufficiency of some component process or substance. "Although abolished SOCE, T cell dysfunction and immunodeficiency in these patients indicate that ORAI1 is the dominant CRAC channel subunit in human effector T cells, these findings do not exclude a potential role of ORAI2 in other immune or non-immune cells in which it is expressed." (PMID 28294127, 2017).
infarct (1 paper, 2022). "Orai2 deficiency significantly halted cerebral infarct progression under occlusion." (PMID 36012752, 2022).
ischemia (1 paper, 2022). A hypoperfusion of the BLOOD through an organ or tissue caused by a PATHOLOGIC CONSTRICTION or obstruction of its BLOOD VESSELS, or an absence of BLOOD CIRCULATION. "Mice lacking Orai2 displayed reduced cerebral damage both during acute ischemia under vessel occlusion and during ischemia–reperfusion upon recanalization." (PMID 36012752, 2022).
ischemic stroke (1 paper, 2020). A stroke disorder caused by obstruction of blood flow to the brain, due to thrombotic (local blood clot formation) or embolic (due to a blood clot or other material traveling from another site) event. "Although both Orai1 and Orai2 contribute to SOCE, they play distinct roles in ischemic stroke." (PMID 33328896, 2020).
melanoma (1 paper, 2014). A malignant, usually aggressive tumor composed of atypical, neoplastic melanocytes. "In contrast, STIM2, Orai2 and Orai3 expression was undetectable or barely detectable in the melanoma cell lines (data not shown)." (PMID 24586666, 2014).
triple-negative breast carcinoma (1 paper, 2021). An invasive breast carcinoma which is negative for expression of estrogen receptor (ER), progesterone receptor (PR), and human epidermal growth factor receptor 2 (HER2). "In the HER2 and triple negative breast cancer cell lines SKBR3 and BT20, respectively, where the expression of Orai2 was greater, Orai2 modulates the magnitude of SOCE and sustain Ca2+ oscillations in response to carbachol." (PMID 35008277, 2021).
type 1 diabetes (1 paper, 2018). "Significant correlation was found for ORAI2 with age of onset of type 1 diabetes (p <0.05) and CaV1.2 (p <0.05) with duration of type 1 diabetes." (PMID 30543678, 2018). "Similar to the expression in PBMCs from pregnant women, the average expression level of ORAI1, ORAI2 and ORAI3 were significantly up-regulated by type 1 diabetes." (PMID 30543678, 2018).